ALKBH5 (alkB homolog 5, RNA demethylase)
Diseases named in the same sentence as ALKBH5 in open-access papers (continued):
Sharing a sentence is not in itself a finding about the gene and the disease.
cancer (289 papers, 2017 to 2026). A tumor composed of atypical neoplastic, often pleomorphic cells that invade other tissues. "Targeted DNA sequencing was conducted on common FTO and ALKBH5 variants previously reported to be associated with cancer risk." (PMID 40361322, 2025). "ALKBH5 is implicated in various cancers, including GBM, where its elevated expression in CSCs, promoting their self-renewal 14-16." (PMID 39990235, 2025). "Dysregulation of m6A machinery, including methyltransferases (METTL3, METTL14), demethylases (FTO, ALKBH5), and m6A readers (YTHDFs, IGF2BPs), has been implicated in oncogenesis, immune evasion, and therapy failure in multiple cancers, including HNSCC." (PMID 41624157, 2025). "Clinical data indicate that high ALKBH5 expression in these cancers is associated with poor prognosis and shows correlations with increased macrophage infiltration and M2 polarization." (PMID 40176140, 2025). "Researchers have found that loss of ALKBH5 is associated with poorer survival in patients with cancer." (PMID 37998339, 2023). "Cancer hallmark‐related pathways, including cancer proliferation and metastasis, are shown in the Circos plot, which indicated a close association of ALKBH5 and cancer proliferation and metastasis." (PMID 36864711, 2023). "Along with the fat mass and obesity-associated protein (FTO), ALKBH5 is one of only two identified human m6A RNA oxidizing enzymes and is a potential target for cancer treatment." (PMID 35333330, 2022). "AlkB homolog 5 (ALKBH5) is a N6-methyladenosine (m6A) demethylase associated with the development, growth, and progression of multiple cancer types." (PMID 35444654, 2022). "Recently, emerging studies have shown that m6A modification by ALKBH5 was associated with immunotherapy response in various types of cancer." (PMID 36566230, 2022). "Genetic alterations including duplications and deep mutations of the ALKBH5 gene were identified in several cancer types." (PMID 35444654, 2022). "During the investigation of underlying mechanisms, a set of functional targets of ALKBH5 were identified in these cancers." (PMID 35063010, 2022). "Although ALKBH5 has also been implicated in some types of cancers, its AML-associated function and mechanism have remained unclear." (PMID 35579750, 2022). "TIMER database analysis showed that BLCA (6/411), BRCA-Her2 (1/79), and UCEC (6/531) were the top 3 cancers with the highest ALKBH5 gene mutation rates." (PMID 35444654, 2022). "cBioPortal database analysis showed that missense mutations were the main type of ALKBH5 gene mutations in cancers." (PMID 35444654, 2022). "AlkB Homolog 5 (ALKBH5), one of epitranscriptomics enzymes, has been identified to be associated with various cancers." (PMID 34112124, 2021). "Functional annotations based on the RNA-seq results suggested that ALKBH5 upregulation was associated with DNA repair processes in cancer cells." (PMID 34496932, 2021). "Only recently has it begun to be realized that ALKBH5 gene SNPs contribute to the genetic predisposition of cancer." (PMID 33790968, 2021). "ALKBH5 gene encodes one of the two known m6A demethylases and is reportedly involved in multiple biological mechanisms related to cancer such as proliferation or metastasis." (PMID 34950106, 2021). "The underlying regulatory mechanisms of ALKBH5 that relys on m6A-dependent modification are implicated with long non-coding RNA, cancer stem cell, autophagy and hypoxia." (PMID 32742194, 2020). "Available evidences also indicate that several members of AlkB family, such as ALKBH3 and ALKBH5, are closely linked to the inhibition of tumorigenesis and progression in various human cancers." (PMID 32478065, 2020). "In the field of cancer research, the underlying mechanisms of ALKBH5 in human cancers were not only unclear but also controversial." (PMID 32742194, 2020). "Only until recently has it begun to be realized that m6A‐SNPs in the ALKBH5 account for genetic predisposition to complex traits, such as cancer." (PMID 32091154, 2020).
cancer (continued). "ALKBH5-mediated demethylation of mRNA N6-methyladenosine has been linked to cancer stem cell phenotypes." (PMID 30149601, 2018). "Conversely, other evidence suggests that ALKBH5 deficiency or low expression may promote immune escape mechanisms, indicating that its predictive value may be context- and cancer-type–dependent." (PMID 41562066, 2025). "The underlying mechanisms of ALKBH5 in human cancers were not only unclear but also controversial." (PMID 39781264, 2025). "Moreover, the upregulation of ALKBH5 is associated with a worse prognosis in patients with these types of cancer." (PMID 40675967, 2025). "There may be some special factor that causes the cancer to grow despite the elevated expression of ALKBH5." (PMID 40448344, 2025). "Single-nucleotide polymorphisms (SNPs) in FTO and ALKBH5 are associated with cancer risk." (PMID 40361322, 2025). "ALKBH5 has been implicated in the regulation of lncRNAs, cancer stem cells, autophagy, and hypoxia." (PMID 39759516, 2024). "Recent studies have linked ALKBH5 overexpression to epigenetic changes in some cancers." (PMID 34759347, 2022). "Therefore, LKB1 expression directly affects the global m6A levels via ALKBH5 in KRAS-mutated cancer cells." (PMID 34016959, 2021). "ALKBH5 has recently been shown to be one of the RNA N6-methyladenosine (m6A) demethyltransferases associated with various cancers, but its role in cancer therapeutic resistance remains unclear." (PMID 34496932, 2021). "In the area of human cancer research, studies have been carried out trying to reveal the underlying regulatory mechanisms of ALKBH5 in human cancers, but it still remains unclear as well as controversial." (PMID 34103054, 2021). "Interestingly, PVT1, a gene significantly associated with OS survival, is upregulated in cancers through ALKBH5-mediated N6-adenosine methylation." (PMID 35095893, 2021). "Thus, the data indicate that LKB1 loss induces DNA hypermethylation, thereby controlling ALKBH5 expression in KRAS mutant cancer cells." (PMID 34016959, 2021). "ALKBH5, the second m6A demethylase, is also associated with several cancers." (PMID 32296573, 2020). "By removing m6A modifications on essential RNAs, ALKBH5 has been shown to be involved in the development and progression of several malignancies, such as breast, lung, colon, pancreatic, and more, with the prognostic association with expression level varying by cancer type." (PMID 40243425, 2025). "ALKBH5 is a well-established regulator of m6A homeostasis, and it has been studied extensively in different types of cancers." (PMID 40603319, 2025). "A key challenge lies in defining the directionality of ALKBH5’s immune effects across distinct tissue environments and cancer types." (PMID 41562066, 2025). "The expression and activity of ALKBH5 are subject to multilayered upstream regulation, particularly in cancer." (PMID 41562066, 2025). "Recent studies have shown that m6A modification is mediated by YTH N6-methyladenosine RNA binding protein F (YTHDF) and reduced by alkB homolog 5 (ALKBH5) across multiple cancers." (PMID 39465506, 2025). "In cancer stem cells, studies have shown that the depletion of FTO and ALKBH5 leads to increased m6A modification, which can significantly reduce the self-renewal ability of cancer stem cells." (PMID 40356596, 2025). "For instance, recent studies demonstrated that deletion of the m6A demethylase ALKBH5 sensitizes tumors to cancer immunotherapy by reducing the accumulation of MDSCs and Tregs within the microenvironment." (PMID 40176140, 2025). "ALKBH5 promotes cancer cell migration and invasion by modulating m6A modifications, a phenomenon confirmed by studies on glioma cells in vitro and in vivo." (PMID 39802639, 2025). "For instance, inhibition of Alkbh5, a demethylase involved in RNA modifications, significantly enhances cancer immunotherapy effectiveness." (PMID 40176140, 2025).
cancer (continued). "Recent studies have highlighted the various roles of FTO and ALKBH5 in tumorigenesis and cancer progression." (PMID 40361322, 2025). "The covalent inhibitor TD19 prevented ALKBH5 from binding to RNA m6A-methylated sites, thereby exerting an anti-cancer effect." (PMID 40001461, 2025). "Eraser proteins (e.g., Fto, Alkbh5) modulate mRNA stability by removing m6A modifications, influencing cancer progression and chemoresistance." (PMID 41208876, 2025). "The elevated levels of ALKBH5 have been identified as an oncogene that can facilitate the growth of cancer cells." (PMID 39746750, 2025). "ALKBH5 promotes the development of reproductive system cancers by increasing the expression of oncogenes." (PMID 40001461, 2025). "ALKBH5 was demonstrated to be upregulated in some cancers, such as glioblastoma stem cells, breast cancer stem cells, colorectal cancer, esophageal cancer, thyroid cancer, gastric cancer, acute myeloid leukemia, and prostate adenocarcinomas." (PMID 40830264, 2025). "Another major gap is cell-type specificity-most work focuses on cancer cells, while the roles of ALKBH5 in dendritic cells, macrophages, NK cells, B cells, and distinct T-cell subsets remain largely unexplored." (PMID 41562066, 2025). "Our findings unveil the epigenetic regulation of cell cycle checkpoint by ALKBH5 in X-ray-induced DNA damage, offering potential targets for DNA damage-based therapy for cancers." (PMID 40341728, 2025). "ALKBH5 supports the maintenance of glioblastoma cancer stem-like cells by stabilizing FOXM1 transcripts." (PMID 41228380, 2025). "Together, these layers of regulation shape the biological functions of ALKBH5 in tumorigenesis and cancer progression." (PMID 41562066, 2025). "Compounds such as 2-[(1-hydroxy-2-oxo-2phenylethyl) sulfanyl] acetic acid (cmp-3) and 4-{[(furan-2-yl)-methyl] amino}-1,2-diazinane-3,6-dione (cmp-6) have been identified as ALKBH5 inhibitors as well, significantly suppressing cancer progression." (PMID 40001461, 2025). "Collectively, these studies indicate that pharmacological inhibition or silencing of FTO and ALKBH5, two critical demethylases, can substantially sensitize cancers to ICI therapy." (PMID 39987091, 2025). "It is intriguing that ALKBH5 is a primary m6A demethylase, which is dysregulated and has a biological and pharmacological role in human cancers." (PMID 39781264, 2025). "RNA demethylase ALKBH5 has been identified as a viable target in cancer treatment due to its role in chemotherapy resistance through m6A demethylation." (PMID 39465506, 2025). "Remarkably, the functional output and clinical relevance of ALKBH5 exhibit remarkable heterogeneity across distinct cancer subtypes, underscoring the complexity of m6A-mediated epigenetic control in malignancy." (PMID 40986143, 2025). "In summary, the abnormal expression of FTO and ALKBH5 affects the expression level of m6A, which further affects the development of cancer, indicating that they have the potential to be prognostic biomarkers for various cancers." (PMID 38166832, 2024). "FOXM1 which plays an important role in cell cycle and genomic stability is the downstream target of ALKBH5 in various cancers." (PMID 39600630, 2024). "By considering that ALKBH5 acts as oncogene in several kinds of cancer cells, we evaluate the effects of ALKBH5 knockdown on malignancies of OV cells, including SkOV3 and ES2." (PMID 38098223, 2024). "Numerous research advances have many research breakthroughs that have underscored the oncogenic significance of FTO and ALKBH5 across a spectrum of cancers." (PMID 38572667, 2024). "In GBM, ALKBH5 worked as an oncogene and influences the self-renewal and proliferation of cancer stem cells." (PMID 38637813, 2024).
cancer (continued). "Future preclinical studies, i.e., using inhibitors of both FTO and ALKBH5, are thus needed to evaluate the role of the ALKBH5 FTO-ATF4 axis in the resistance of cancer cells to treatment." (PMID 39199320, 2024). "Understanding the distinct mechanisms of action of FTO and ALKBH5 in tumors is crucial for unraveling the molecular underpinnings of cancer development and providing insights for developing targeted therapeutic strategies." (PMID 39192357, 2024). "ALKBH5 has a key role in many important cellular procedures and contributes to the development and progression of cancer." (PMID 38572667, 2024). "Patients with strong nuclear expression patterns of ALKBH5 exhibit greater sensitivity to anti‐PD‐1 therapy, emphasising the diverse functions of m6A regulators across cancer types." (PMID 38545841, 2024). "ALKBH5 is a m6A RNA demethylase, and the role of m6A components in cancer is only just being revealed." (PMID 39127986, 2024). "CESC, BRCA, LUAD, and COAD cell lines express lower amounts of METTL3 and FTO transcripts compared to their healthy counterparts, while WTAP and ALKBH5 expressions differ by cancer type." (PMID 38665783, 2024). "ALKBH5 plays a critical role in autophagy, stem-cell renewal, cell proliferation, metastasis, and radioresistance in various cancers." (PMID 39600630, 2024). "A growing body of evidence indicates that ALKBH5 is commonly dysregulated in malignant tumors, which regulates the expression of multiple oncogenes and contributes to tumor immune evasion through post-transcriptional mechanisms." (PMID 39054967, 2024). "ALKBH5 demethylates m6A modifications, maintaining the stability of specific RNAs and regulating specific gene splicing processes, thereby affecting cancer cell proliferation and migration." (PMID 39295872, 2024). "Here, we show that shRNA-mediated depletion of ALKBH5 or FTO (using a lentiviral system) significantly decreased ATF4 protein levels in SOR-treated Hep3B cancer cells." (PMID 39199320, 2024). "Consistent with previous studies in cancer, a range of ALKBH5 staining was identified in the nuclear and cytoplasmic compartments of cells." (PMID 39127986, 2024). "ALKBH5 has a context-dependent role and functions both as a tumor suppressor and carcinogen in different cancers and even in the same cancer type." (PMID 39087001, 2024). "These revelations pave the way for further exploration of the roles played by ALKBH5 in the pathogenesis of diverse human carcinomas." (PMID 38501918, 2024). "The m6a demethyltransferase ALKBH5 dynamically modulates gene expression and intracellular metabolic molecules by modifying RNA m6a in cancer cells." (PMID 38007439, 2023). "ALKBH5 regulates cell cycle, autophagy, DNA repair, metabolism, immune response, and other cellular processes in cancer." (PMID 37096833, 2023). "FTO has the similar structure with ALKBH5 in core domain and is closely related to obesity and cancer." (PMID 37264402, 2023). "KO of ALKBH5 inhibited cancer cell proliferation, colony formation, migration, and invasion in HeLa cells." (PMID 37369679, 2023). "In RCC, the expression levels of ALKBH5 and FTO are associated with shorter overall and cancer-specific survival after nephrectomy and can be used as prognostic biomarkers." (PMID 38117350, 2023). "Promising treatment options such as small-molecule modulators, compounds targeting the regulators of ALKBH5, and gene therapy have been expected to manipulate ALKBH5-mediated m6A demethylation in cancer." (PMID 37915103, 2023). "IHC analysis of 74 HPSCC patients in Cohort 1 and Cohort 2 confirmed that the expression level of ALKBH5 in cancer tissues was much lower than that in paired normal tissues." (PMID 37612282, 2023).
cancer (continued). "K235 acetylation is upregulated in cancers and critical for the m6A demethylation activity and oncogenic functions of ALKBH5." (PMID 37369679, 2023). "As an m6A demethylase, ALKBH5 has been shown to contribute to the progression of different cancers by increasing expression of several oncogenes." (PMID 37858219, 2023). "In ovarian cancer, ALKBH5 promotes cisplatin resistance in cancer cells by modifying its m6A target gene JAK2 to activate the JAK2/STAT3 signaling pathway." (PMID 36609413, 2023). "Collectively, all the evidence suggested that ALKBH5 acted as a cancer‐promoting regulator in GC in vitro and in vivo." (PMID 36864711, 2023). "It is worth noting that that hypoxia, epigenetic modulators, transcription factors, and ncRNAs act as main contributors to ALKBH5 dysregulation in cancer." (PMID 37915103, 2023). "Only after recognizing FTO and ALKBH5 as mRNA demethylases have their epigenetic regulatory roles in cancers been gradually emphasized." (PMID 37007161, 2023). "We also demonstrate that ALKBH5-cIDR is indispensable for hypoxia-induced effects such as cancer cell invasion." (PMID 37474102, 2023). "This is consistent with the trend that increasing proline or ALKBH5 overexpression promotes GBM or cancer progression." (PMID 37325047, 2023). "ALKBH5 level is high-expression in various cancer tissues, such as lung cancer and epithelial ovarian cancer but down-regulated in hepatocellular carcinoma, colon cancer and bladder cancer cells." (PMID 37598390, 2023). "KO and KD of ALKBH5 inhibited cancer cell proliferation, colony formation, migration, and invasion in vitro and tumorigenesis in vivo." (PMID 37369679, 2023). "Conversely, the addition of serum to serum-starved cancer cells enhanced the ALKBH5 K235 acetylation level within 3 h." (PMID 37369679, 2023). "In the current study, we have uncovered the upregulated ALKBH5 activated FABP5 to promote the lipid metabolism of cancer." (PMID 37858219, 2023). "Current studies have revealed dysregulation of ALKBH5 expression in various cancers, including lung, breast, and gastric cancer." (PMID 38094306, 2023). "M6A modifications which are installed by methyltransferases (METTL3, METTL14) and removed by RNA demethylases (FTO, ALKBH5) are widely investigated in cancers." (PMID 38007439, 2023). "Gain- and loss-of-function assays were employed in the scrutiny of the biological effects of the ALKBH5/YY1/ATG4B axis on cancer cell proliferation and invasion abilities in vitro." (PMID 37724907, 2023). "Demethylase ALKBH5 is up‐regulated in several solid tumors and can be a biomarker for some malignant tumor prognosis, such as NSCLC and CRC." (PMID 36260366, 2023). "Recently, ALKBH5-induced m6A demethylation was found to play crucial roles in numerous diseases, especially cancer and sepsis." (PMID 36859428, 2023). "Recent findings suggested that hypoxia, as well as some epigenetic modulators, transcription factors and non-coding RNAs are main contributors to ALKBH5 dysregulation in cancer." (PMID 35063010, 2022). "Soon after its identification as an m6A eraser, ALKBH5 was found to be involved in the initiation and progression of various cancers." (PMID 34759347, 2022). "It has been highlighted that an enhanced population of cancer stem cells (CSCs) contributes to chemoresistance and recurrence, and that ALKBH5 promoted CSC property through increasing FOXM1 and NANOG." (PMID 35628623, 2022). "Dysregulation of these processes is frequently observed in human cancers, some of which are responsible for ALKBH5 dysregulation in cancers." (PMID 35063010, 2022). "To date, FTO and ALKBH5 have been widely reported in modulating RNA m6A modification in various human cancers." (PMID 35936737, 2022). "A previous study showed that decreased ALKBH5 mRNA levels correlated with shortened overall and cancer-specific survival in ccRCC." (PMID 36528763, 2022).